FSCN1 (fascin actin-bundling protein 1)
Diseases named in the same sentence as FSCN1 in open-access papers (continued):
Sharing a sentence is not in itself a finding about the gene and the disease.
chondrosarcoma (4 papers, 2021 to 2025). A malignant cartilaginous matrix-producing mesenchymal neoplasm arising from the bone and soft tissue. "The downregulation of miR-143/145 in Chondrosarcoma leads to increased expression of FSCN1, which facilitates cytoskeletal remodeling and promotes metastatic behavior of tumor cells." (PMID 40429954, 2025). "A study demonstrated that down-regulation of these miRNAs in chondrosarcoma triggers up-regulation of FSCN1, thus promoting tumor progression and metastasis." (PMID 38542153, 2024). "Thus, this highlights the crucial role of FSCN1 and the miRNAs that regulate it in the pathogenesis of chondrosarcoma." (PMID 38542153, 2024).
head and neck cancer (4 papers, 2021). A primary or metastatic malignant neoplasm affecting the head and neck. "documented that snail family transcriptional repressor 2 (SNAI2) elevates the expression of FSCN1 at both mRNA and protein levels in head and neck cancer cells by binding the FSCN1 promoter." (PMID 33614909, 2021). "For example, more than 80% of bladder, as well as head and neck cancer tissues, express high levels of FSCN1." (PMID 33614909, 2021). "In head and neck cancer cells, SNAIL2 was found to directly bind to the FSCN1 promoter, inducing FSCN1 expression." (PMID 34830909, 2021).
liver cancer (4 papers, 2020 to 2024). An epithelial or non-epithelial malignant neoplasm that arises from the liver. "Currently, a few studies have reported on the expression of FSCN1 in liver cancer, showing that FSCN1 is highly expressed in both HCC and ICC, and is associated with poor patient prognosis." (PMID 38698008, 2024). "It was found that UCHL5 facilitated filopodia formation in liver cancer cells by regulating FSCN1, which was associated with FASN." (PMID 39075049, 2024). "The results indicated that FASN was closely associated with liver cancer migration and invasion, and interacted with FSCN1, SIPA1, SPTBN1 and CD59." (PMID 32699531, 2020). "Further investigation of FSCN1’s clinical implications in liver cancer and its potential as a therapeutic target is warranted." (PMID 38698008, 2024). "Previous studies have reported on the expression and clinical significance of FSCN1 in liver cancer." (PMID 38698008, 2024). "Although some studies have reported on the expression and clinical significance of Fascin-1 (FSCN1) in liver cancer, the clinical application and differential diagnosis value of FSCN1 in liver cancer are still unclear." (PMID 38698008, 2024). "In conclusion, the current study identified that FASN is upregulated in liver cancer and then promotes filopodia formation and metastasis of liver cancer cells by regulating FSCN1 and other pathways." (PMID 39075049, 2024). "In this study, we demonstrated that fatty acid synthase (FASN) promoted filopodia formation in liver cancer cells by regulating fascin actin-bundling protein 1 (FSCN1), a marker protein for filopodia." (PMID 39075049, 2024). "This study selected 108 cases of HCC, 26 cases of ICC, 23 cases of liver cirrhosis, and 11 cases of normal liver tissue to elucidate the expression of FSCN1 in liver tissue and its clinicopathological significance in the occurrence and development of liver cancer." (PMID 38698008, 2024). "In our study, we confirmed that FASN could positively regulate FSCN1 and determined that FASN could promote filopodia formation in human liver cancer cells by regulating FSCN1." (PMID 39075049, 2024). "Despite this, it remains uncertain whether there are variances in the manifestation of FSCN1 among various histological types of liver cancer, such as HCC and ICC, as well as its correlation with different clinicopathological characteristics of patients." (PMID 38698008, 2024). "In the current study, silencing of FASN, FSCN1 or SPTBN1 expression in liver cancer cells led to changes in the mRNA expression of EMT-associated markers, E-cadherin, N-cadherin, vimentin and transcription factors Snail and Twist, and altered the protein expression of MMP-2 and MMP-9." (PMID 32699531, 2020). "Knockdown of FASN in liver cancer reduced the expression of FSCN1, SIPA1, SPTBN1 and CD59." (PMID 32699531, 2020). "Recent studies revealed that FASN directly regulates FSCN1 which participates in the formation of filamentous pseudopodia, lamellar pseudopodia, and microspines and the coding of cytoskeletal proteins, thus promoting the migration and invasion of liver cancer cells." (PMID 39075049, 2024). "Furthermore, co-precipitation and co-localization of FASN with FSCN1 and SIPA1 in liver cancer indicated that FASN may mediate tumor metastasis via the PI3K/NF-κB/MMPs signaling pathway through interactions with FSCN1 or SIPA1." (PMID 32699531, 2020). "In this study, we determined that ADRM1-activated UCHL5 was upregulated in liver cancer and stabilized FASN through deubiquitinating it, thereby promoting the expression of FSCN1 and filopodia formation in human liver cancer cells, as well as cell movement." (PMID 39075049, 2024). "In the current study, FSCN1 and SIPA1 were significantly downregulated following FASN knockdown in liver cancer cells." (PMID 32699531, 2020). "To confirm whether FSCN1 was involved in filopodia formation and cell movement regulated by FASN, we transfected Myc-tagged FSCN1 into FASN-silenced liver cancer cells." (PMID 39075049, 2024).
liver cancer (continued). "To confirm whether SIAH1 affects filopodia formation in liver cancer cells by regulating FASN, we detected the regulation of FSCN1 by SIAH1." (PMID 39075049, 2024). "The results showed that SIAH1 could decrease the expression of FSCN1 by directly ubiquitinating FASN, thereby inhibiting filopodia formation in human liver cancer cells, as well as cell invasion and migration." (PMID 39075049, 2024).
lymph node metastasis (4 papers, 2013 to 2025). "Additionally, we also observed that FSCN1 expression is significantly associated with a number of clinical parameters of IDC patients, including tumor size (P = 0.024), grade (P < 0.0001), stage (P = 0.045), ER- (P < 0.0001), PR- (P < 0.0001) and axillary lymph node metastasis (P = 0.024)." (PMID 29142206, 2017). "In HNSCC patients with lymph node metastases (T2–4N1M0), serum levels of FSCN1 were 10-fold higher than in patients without clinically confirmed regional lymph node metastases (T1–4N0M0; P < 0.05)." (PMID 40669873, 2025).
metastatic disease (4 papers, 2014 to 2021). "The analysis of FSCN1 mRNA expression in different PCa datasets showed a quite limited diagnostic role of FSCN1, although increased in metastatic disease." (PMID 34737886, 2021). "Although this protein can also be expressed in normal tissues, recent studies have shown that FSCN1 is up-regulated in many types of metastatic tumors, and its expression correlates with enhanced aggressiveness, poor prognosis, and reduced survival." (PMID 34248854, 2021). "Several systematic reviews and meta-analyses have established that FSCN1 is a potential biomarker for the identification of aggressive metastatic tumors or prognosis." (PMID 33614909, 2021). "Systematic reviews and meta-analyses have revealed that FSCN1 is correlated with increased mortality risks and metastasis in various cancer types, is a novel biomarker for the identification of aggressive and metastatic tumors, and is a prognostic marker of overall survival." (PMID 33614909, 2021).
oral squamous cell carcinoma (4 papers, 2020 to 2023). "For example, lncRNA PRNCR1 directly binds to miR-326, thereby functioning as a miR-326 “sponge” to up-regulate the expression level of fascin actin-bundling protein 1(FSCN1) in oral squamous cell carcinoma." (PMID 35197980, 2022).
cervical tumor (3 papers, 2021 to 2025). "Expression analysis in TCGA (The Cancer Genome Atlas) revealed that FSCN1 had negative correlations with several transcription factors and a positive correlation with an angiogenic factor (angiopoietin like 4, ANGPTL4) in cervical tumor tissue." (PMID 35178306, 2022).
cholangiocarcinoma (3 papers, 2021 to 2022). A carcinoma that arises from the intrahepatic biliary tree (intrahepatic cholangiocarcinoma) or from the junction, or adjacent to the junction, of the right and left hepatic ducts (hilar cholangiocarcinoma). "documented that FSCN1 promotes cholangiocarcinoma cell EMT by regulating Wnt/β-catenin signaling." (PMID 33614909, 2021).
diabetes (3 papers, 2021 to 2024). "Moreover, serum FSCN1 levels were significantly higher in ACC patients compared with obese/T2D patients, who have higher levels of FSCN1, probably due to kidney overload/damage associated to diabetes, as already demonstrated in renal injury associated with renal transplantation." (PMID 34248854, 2021).
laryngeal squamous cell carcinoma (3 papers, 2020 to 2025). A squamous cell carcinoma that arises from the larynx. "Studies have reported significant FSCN1 expression in laryngeal squamous cell carcinoma tissues, suggesting its role in the malignant progression of this cancer." (PMID 40818124, 2025).
leukemia (3 papers, 2018 to 2025). A malignant (clonal) hematologic disorder, involving hematopoietic stem cells and characterized by the presence of primitive or atypical myeloid or lymphoid cells in the bone marrow and the blood. "These opposing correlations of DLG4-leucine and FSCN1-malic acid between leukemia and BPO suggest possible tissue-specific relationships that can be differentially targeted." (PMID 29506475, 2018). "FSCN1 and malic acid are positively correlated in leukemia (r = 0.94) but negatively correlated in BPO cancers (r = − 0.75)." (PMID 29506475, 2018). "Several of the top 20 APL super enhancers are linked to genes known to have functional roles in leukemia, for example RNF216, FSCN1, FNDC3B, HSP90B1, C12orf75, and JARID2, among them, JARID2 is a hematopoietic tumor suppressor through recruiting PRC2 to repress self-renewal pathways." (PMID 41168841, 2025).
liver fibrosis (3 papers, 2021 to 2023). "We demonstrated a new cellular mechanism by which CVC inhibits ECM accumulation in liver fibrosis by suppressing the hepatic accumulation of inflammatory FSCN1+ macrophages and HERC6+ neutrophils." (PMID 37215993, 2023). "CVC ameliorates ECM deposits and liver fibrosis by suppressing the hepatic accumulation of inflammatory FSCN1+ macrophages and HERC6+ neutrophils." (PMID 37215993, 2023).
mastitis (3 papers, 2021 to 2025). Inflammation of breast tissue during lactation or postpartum due to an obstructed duct or infection. "Furthermore, the downregulation of miR-145 in response to Staphylococcus aureus-induced mastitis, through the targeting of FSCN1 in dairy cows, plays a crucial role in regulating immune response." (PMID 40005551, 2025). "In dairy cows with Staphylococcus aureus-induced mastitis, immune cytokines are regulated by miR-145, which targets and regulates FSCN1, and downregulating miR-145 and upregulating FSCN1 expression promotes mammary epithelial cell proliferation and accelerates the recovery of damaged tissues." (PMID 34211501, 2021).
oral cancer (3 papers, 2021 to 2024). "A recent study established that the CREB signaling pathway is involved in interleukin (IL)-1β-induced FSCN1 expression in human oral cancer cells." (PMID 33614909, 2021). "This analysis revealed that in addition to the positive control GAPDH, all oral cancers upregulated the miR-145 downstream targets MBTD1 and FSCN1." (PMID 38396844, 2024). "In addition, several downstream targets of these specific microRNAs were upregulated by all oral cancer cell lines, such as MBTD1 and FSCN1, or downregulated in all cell lines, such as CLCN3, FLI-1, MRTFB, DAB, SRGAP1, and ABHD17C." (PMID 38396844, 2024). "On literature search for proteomic profiling of POSTN, TNC, CAV1 and FSCN1 in OSCC or oral cancer, we could not find any related studies reported till date." (PMID 33739025, 2021).
osteoarthritis (3 papers, 2024 to 2026). A noninflammatory degenerative joint disease occurring chiefly in older persons, characterized by degeneration of the articular cartilage, hypertrophy of bone at the margins and changes in the synovial membrane. "Moreover, targeted knockdown of Fscn1 for osteoarthritis treatment using RDLot-ABE alleviates cartilage degradation in explants derived from human patients." (PMID 42052652, 2026). "Notably, intra-articular delivery of the RDLot-ABE to reduce Fscn1 effectively arrests disease progression in a murine osteoarthritis model." (PMID 42052652, 2026). "Interestingly, Adam8 demonstrates protective effects in osteoarthritis by inhibiting fibroblast-like synoviocyte migration and invasion through the FSCN1/MAPK pathway." (PMID 41008561, 2025).
triple-negative breast carcinoma (3 papers, 2017 to 2024). An invasive breast carcinoma which is negative for expression of estrogen receptor (ER), progesterone receptor (PR), and human epidermal growth factor receptor 2 (HER2). "They further confirmed the possible functional relevance of FSCN1 expression in the development of Triple-Negative Breast Cancer (TNBC) because it was substantially higher in TNBC than in the non-TNBC subtype." (PMID 38587571, 2024). "However, the regulatory mechanism of FSCN1 in triple-negative breast cancer (TNBC) cell invasion and migration is still largely unknown." (PMID 29142206, 2017).
acute myeloid leukemia (2 papers, 2021 to 2023). Acute myeloid leukemia (AML) is a group of neoplasms arising from precursor cells committed to the myeloid cell-line differentiation. "Among the 31 tumor types studied, FSCN1 was highly expressed in 16 tumor types ( P < 0.05), whereas FSCN1 expression was significantly lower in acute myeloid leukemia tissues (P < 0.05)." (PMID 38077434, 2023).
adrenocortical adenoma (2 papers, 2019 to 2021). "FSCN1 and FOXM1 were over-expressed in ACC tissue when compared with adrenocortical adenoma and normal adrenal tissue." (PMID 31783819, 2019).
adult T-cell leukemia (2 papers, 2021 to 2022). "A recent study in adult T-cell leukemia/lymphoma (ATLL) with HTLV-1–infected Hodgkin and Reed-Sternberg–like cells found elevated FSCN1 expression." (PMID 34830909, 2021).
asthma (2 papers, 2015 to 2024). "By using the LASSO algorithm, we identified five shared eosinophil‐associated hub genes (PPP1R14A, FNBP1, DRAM1, FSCN1, and MMP12) in asthma and CC." (PMID 39659035, 2024). "We found that RAMP1, FSCN1, PSTG1 and SPINT2 genes could be associated with the development of severity of asthma." (PMID 26302899, 2015). "However, no studies showed an association of FSCN1 (fascin actin-bundling protein 1) and SPINT2 (serine peptidase inhibitor, Kunitz type, 2) with the evolution of asthma severity." (PMID 26302899, 2015).
breast tumors (2 papers, 2015 to 2024). "Recently, the relationship of FSCN1 and HOTAIR polymorphisms with breast tumor development has been investigated." (PMID 38587571, 2024).
carcinoids (2 papers, 2021 to 2023). "Positive FSCN1 expression is detected in 5% of typical carcinoid tumors, 35% of atypical carcinoid tumors, 83% of large-cell neuroendocrine lung cancer, and 100% of small-cell lung cancer." (PMID 38077434, 2023).
cervical squamous cell carcinoma (2 papers, 2021). A squamous cell carcinoma arising from the cervical epithelium. "In addition, a study in Iran was carried out to investigate the prevalence of HPV and FSCN1 in cervical squamous cell carcinoma and found an association between FSCN1 overexpression and HPV positivity." (PMID 34830909, 2021).
colorectal adenoma (2 papers, 2015 to 2021). An adenoma that arises from the colon or rectum. "In the colon as well, FSCN1 expression is higher in sporadic and familial colorectal adenomas and adenocarcinomas as compared to the healthy colon; FSCN1 expression was reported to progress from focal during the early stages to diffused in the advanced stages." (PMID 34830909, 2021).
COVID-19 (2 papers, 2022). A disease caused by infection with severe acute respiratory syndrome coronavirus 2. "A total of 6 hub genes were obtained, including: LDHA, TRPA1, PKP2, FBN2, ERO1A, FSCN1, all of which are risk factors for LUAD/COVID-19." (PMID 36157452, 2022).
ductal adenocarcinoma (2 papers, 2017 to 2023). "In our study, we observed that the FSCN1 expression rates were significantly higher in invasive ductal carcinoma, compared with both usual ductal hyperplasia and ductal carcinoma in situ." (PMID 29142206, 2017).
metastatic melanoma (2 papers, 2021 to 2025). A melanoma that has spread from its primary site to another anatomic site. "Critically, FRA1 directly activates AXL, CDK6, and FSCN1, which are upregulated in metastatic melanoma and correlate with poor patient outcomes." (PMID 41286309, 2025).
Obesity (2 papers, 2021 to 2024). Accumulation of substantial excess body fat. "This regulatory action of FSCN1 may be because CRC is closely related to obesity and lipid metabolism." (PMID 35069968, 2021). "In this study, bioinformatics analyses indicated that FSCN1 was notably upregulated in the WAT of patients with T2DM and obesity." (PMID 37597213, 2024). "This study identified CIDEA and FSCN1 as key DEGs in intra-abdominal large omental WAT in T2DM patients with obesity and those with simple obesity at the molecular, tissue, human, and gene levels." (PMID 37597213, 2024). "The low expression of CIDEA and high expression of FSCN1 in the T2DM and obesity groups were verified in clinical samples (P < 0.05)." (PMID 37597213, 2024).
prostate tumors (2 papers, 2023 to 2024). "Furthermore, another study assessed FSCN1 immunostaining in 211 prostate tumors and found that only 8% of the tumors had >10% FSCN1 positive cells." (PMID 37634036, 2024).
renal carcinoma (2 papers, 2021 to 2022). A carcinoma arising from the epithelium of the renal parenchyma or the renal pelvis. "FSCN1 expression is increased in actively growing renal carcinoma cell lines 7 compared with that in normal kidney cells." (PMID 35711849, 2022).
renal cell carcinoma (2 papers, 2022). "Similarly, increased FSCN1 levels are associated with aggressiveness of renal cell carcinoma in patients." (PMID 35711849, 2022). "Inhibition of PI3K/AKT or knockdown GSK-3b could decreased the expression of FSCN1, and then attenuated renal cell carcinoma invasion." (PMID 36085041, 2022).
squamous cell carcinoma (2 papers, 2021). A carcinoma arising from squamous epithelial cells. "The overexpression of FSCN1 protein was also reported in vulvar cancer; however, immunostaining failed to distinguish in situ from invasive lesions as well as putative HPV-associated and HPV-independent squamous cell carcinomas." (PMID 34830909, 2021). "In addition, in the squamous cell carcinoma, especially head and neck squamous cell carcinoma, FSCN1 upregulation is frequently high." (PMID 33614909, 2021). "Furthermore, cervical endothelial cells had constant FSCN1 staining, whereas, in CIN lesions and invasive squamous cell carcinomas, there was high FSCN1 expression." (PMID 34830909, 2021).
synovitis (2 papers, 2024). Inflammation of a synovial membrane. "Moreover, treatment with ALK1 inhibitor LDN-193719 attenuated both cartilage destruction and synovitis inflammation caused by FSCN1-OE." (PMID 39231936, 2024). "Our study indicates that the ADAM8/FSCN1/MAPK signaling axis may play a crucial role in the progression of OA-related synovitis." (PMID 38218854, 2024).
tongue SCC (2 papers, 2012 to 2019). "miR-133b targets MET in CRC cells; PKM2 in tongue SCC; FSCN1 in ESCC and myeloid cell leukemia sequence 1 (MCL1); and BCL2-like 2 (BCL2L2) in lung cancer." (PMID 22308266, 2012).